ICAM1 (intercellular adhesion molecule 1)
Diseases named in the same sentence as ICAM1 in open-access papers (continued):
Sharing a sentence is not in itself a finding about the gene and the disease.
diabetes (continued). "Soluble Intercellular Adhesion Molecule 1 (sICAM-1) is an inflammatory marker that has been associated with several common diseases such as diabetes, heart disease, stroke, and malaria." (PMID 18604267, 2008). "Several studieshave reported increased plasma levels of E-selectin and ICAM-1 in patients withhypertension, diabetes, and hypercholesterolemia; moreover in patients at cardiovascular risk, plasma concentration of ICAM-1 canpredict adverse outcome." (PMID 18437228, 2008). "Meta-analysis demonstrated that ICAM1, a cell adhesion molecule, is elevated in the circulatory system of diabetic patients, and its levels are dose-dependently associated with the risk of diabetes." (PMID 38167125, 2024). "The levels of serum ICAM1 are increased in diabetes and its expression has been associated with DN." (PMID 35806457, 2022). "Importantly, the loss of PAR-1 and the increase in ICAM-1 were not limited to STZ-induced diabetes as aortic endothelial cells from Ins2Akita diabetic mice displayed a similar phenotype." (PMID 33258989, 2020). "Furthermore, a clinical study showed a remarkable association between the genotype distribution or the allele frequency of the ICAM-1 K469E polymorphism and the risk to develop DR in type 2 diabetes mellitus patients." (PMID 33291318, 2020). "Retinal capillary endothelium damage in diabetes occurs due to basement membrane thickening, pericyte loss, increased expression of intercellular adhesion molecule-1 (ICAM-1), advanced glycation end products (AGEs), oxidative and nitrosative stress and decreased capillary perfusion." (PMID 29657836, 2018). "In wildtype C57Bl/6J mice, diabetes caused metabolic and physiologic abnormalities in the retina, including increased superoxide production, leukostasis, increased expression of ICAM-1 and iNOS, and subnormal expression of HO-1." (PMID 26426815, 2015). "Changes in gene expression associated with diabetes like increased ICAM-1 expression may also play a role in inducing inflammation and the development of diabetic complications." (PMID 25126086, 2014). "Our results indicate diabetes-induced up-regulation of ICAM1 is associated with VEGF up-regulation." (PMID 24358357, 2013). "High ICAM1 levels in T1D patients are associated with a relative risk of 1.67 (95 CI 0.96–2.92, P = 0.03) of developing incident sustained microalbuminuria after adjustment for baseline age, sex, duration of diabetes, and randomized treatment assignment." (PMID 23346076, 2012). "Our research has been focused on investigating whether alterations in the ICAM1 gene structure and function are associated with the development of diabetes and DN." (PMID 23346076, 2012). "Recently, the accumulating reports from genetic studies in diabetic patients with and without DN and from biological studies with diabetic animal models have implicated that ICAM1 may play a role in the pathogenesis of diabetes and DN." (PMID 23346076, 2012). "Second, the K469E polymorphism in the ICAM1 gene is associated with diabetes and DN." (PMID 23346076, 2012). "Macrophages are known to cause early glomerular injury in STZ-induced diabetes and also to be involved in the mechanisms that cause progressive glomerular and tubular damage; in addition, ICAM-1 and MCP-1 are considered as a central molecule involved in macrophage influx in DN." (PMID 21663638, 2011). "While circulating levels of soluble Intercellular Adhesion Molecule 1 (sICAM-1) have been associated with diverse conditions including myocardial infarction, stroke, malaria, and diabetes, comprehensive analysis of the common genetic determinants of sICAM-1 is not available." (PMID 18604267, 2008). "Interestingly, both in in vitro and in vivo models of diabetes, the overexpression of endothelial adhesion molecules (ICAM-1, VCAM-1, Selectins), and of the enzymes implicated in their O-GlcNAcylation induced by high glucose levels, were significantly decreased by miR-200a and miR-200b mimics." (PMID 31396056, 2019).
diabetes (continued). "Thus, ICAM1 rs5498 might be a risk factor for DN in Caucasians and type 1 diabetes mellitus patients, which suggested that ICAM1 rs5498 might help in early diagnosis and prevention of this disease." (PMID 30587209, 2018). "Our results showed that diabetes or HG-induced increases in arginase expression and activity in retinal vessels and ECs were associated with decreases in NO, increases in ROS formation, leukocyte adherence to the vessel wall, elevated ICAM-1 expression and death of retinal ECs." (PMID 23840196, 2013). "Therefore, we concluded that ICAM1 is associated with diabetes and DN." (PMID 23346076, 2012). "In support of our findings, EMPA-treated patients with diabetes had decreased ICAM-1 circulating levels 24 weeks (6 months) after treatment initiation." (PMID 39958474, 2025). "A recent meta-analysis identified the ICAM-1 rs5498 polymorphism as a risk factor for T2DM, particularly in Asian populations, underscoring the role of immune–inflammatory pathways in diabetes pathogenesis." (PMID 41502515, 2025). "Global REDD1 deletion attenuated STZ-diabetes induced renal mRNA expression of proinflammatory genes including Ccl5, Vegfa, and Icam-1." (PMID 39920111, 2025). "ELISA's findings were consistent with the quantitative RT-PCR results in that the levels of ICAM-1 and VCAM-1 in diabetes rats were much greater than in normal rats, but the treatment of 1,25-D3 reduced the expression levels of ICAM-1 and VCAM-1." (PMID 40224490, 2025). "Silencing APOC3 prevented diabetes-augmented albuminuria, renal glomerular hypertrophy, monocyte recruitment, and macrophage accumulation, partly driven by reduced ICAM1 expression." (PMID 38743496, 2024). "In summary, this SMR analysis explored the potential causal effects of OS-related genes on diabetes and its microvascular complications, highlighting the significant roles of TP53INP1, CHEK1, SUOX, and ICAM1 in the pathogenesis." (PMID 39199149, 2024). "Animal studies showed that diabetes significantly increased ICAM1 expression on the luminal surface of the vascular endothelium, with the highest induction in the mouse retina." (PMID 39199149, 2024). "The current study found that diabetes increased ICAM-1 gene expression in animals compared to the control group, corroborated by previous similar studies." (PMID 39742025, 2024). "Diabetes significantly upregulated ICAM-1 levels, and endothelial cell MICU1 knockout further intensified this change in diabetic MICU1ecKO mice." (PMID 37592255, 2023). "Another study found that ICAM1 in a male rat model of diabetes plays a key role to promote the macrophage infiltration in glomeruli and they showed that block the activity of ICAM1 ameliorates DN50." (PMID 36755074, 2023). "The results of ICAM1 gene expression showed that induction of diabetes only in female group of offspring of DC parents markedly (p < 0.001) increased the expression of this gene in compared to the female offspring of NDC parents." (PMID 36755074, 2023). "Our results showed that diabetes induction just increases ICAM1 gene expression in the male group compared to male NDC group." (PMID 36755074, 2023). "While DR exhibits features of chronic neuroinflammation and inflammatory cytokines have been shown to activate cellular senescence, senescent cells also contribute to inflammation and ICAM-1 expression in diabetes." (PMID 37345657, 2023). "Deleting MyD88 or TLR2/4 from bone marrow-derived immune cells significantly reduces diabetes-induced pathological changes in the retina such as leucostasis, vascular permeability, superoxide generation and intercellular adhesion molecule 1 (ICAM-1)." (PMID 38983565, 2022). "The diabetes-induced increases in the level of inflammatory proteins iNOS and ICAM-1, and in the ratio of pIκB/IκB in the neural retina were inhibited in Akt2 cKO diabetic mice compared to Akt2fl/fl diabetic controls." (PMID 36229454, 2022).
diabetes (continued). "Taken together, these data suggest that Akt2 in the RPE promotes the diabetes-induced increase of neural retinal inflammation that mediates leukostasis within the retinal vasculature through ICAM-1." (PMID 36229454, 2022). "Another prospective study of subjects with diabetes showed an association of plasma levels of TNF and ICAM1 with development of PN." (PMID 35651981, 2022). "Similar to the retina, the diabetes-induced increase in ICAM-1 and iNOS protein was inhibited in the RPE from Akt2 cKO diabetic mice compared to the controls." (PMID 36229454, 2022). "According to cross-sectional studies, VCAM-1 circulating level and ICAM-1 circulating level in diabetes sufferers with nephropathy are higher than those in patients without renal injury." (PMID 35692405, 2022). "Diabetes-induced expression of ICAM-1 and GFAP in the retina were attenuated in REDD1−/− mice, as compared to REDD1+/+ mice." (PMID 36309088, 2022). "ICAM-1 is well recognized to participate in development of diabetes and thereafter inflammatory cell infiltration." (PMID 34104203, 2021). "The adoptive transfer of Tregs decreased the intercellular adhesion molecule 1 (ICAM-1) in the diabetic pancreas and decreased the production of IFN-γ." (PMID 35008819, 2021). "In rodent models of diabetes, modulating the Ang/Tie pathway through Ang-1 overexpression suppressed leucocyte adhesion by significantly reducing retinal ICAM-1 and VEGF protein levels versus controls (both P < 0.001)." (PMID 33564135, 2021). "Increased expression of retinal ICAM-1 and enhanced adhesion of circulating leukocytes to the retinal microvascular endothelium are crucial in the development of diabetes-induced retinal endothelial cell damage and breakdown of BRB." (PMID 35082694, 2021). "Other studies also found higher levels of serum ICAM-1 in patients with diabetes compared with controls." (PMID 33585030, 2021). "Pancreatic expression of IL-10 can up-regulate the expression of intercellular adhesion molecule 1 (ICAM-1) on vascular endothelium and promotes diabetes development, but systemic IL-10 is dispensable for autoimmune diabetes." (PMID 34394099, 2021). "IL-1β contributes to increase the secretion of intercellular adhesion molecule-1, which is responsible for islet beta-cell injury and death, further exacerbating diabetes." (PMID 34938667, 2021). "Intravitreal treatment with TIMP-3 attenuated diabetes-induced upregulation of the pro-inflammatory transcription factor NF-κB and the adhesion molecule ICAM-1." (PMID 35082694, 2021). "As previously reported, diabetes of 2 months duration resulted in a significant increase in expression of retinal iNOS and ICAM-1 in diabetic male mice." (PMID 32941450, 2020). "While the induction of diabetes led to the loss of the N-terminal of the PAR-1 receptor on aortic endothelial cells and a concomitant induction of ICAM-1, the animals given the calpain inhibitor were protected." (PMID 33258989, 2020). "In diabetes, patients also demonstrated increased intercellular adhesion molecule-1 (ICAM-1) in the serum." (PMID 33255669, 2020). "Our data indicated that plasma soluble intercellular adhesion molecule-1 (sICAM-1) and endothelial selectin (e-selectin) were increased in patients with diabetes and diabetic rats." (PMID 33028948, 2020). "We also show that islets of diabetes‐prone animals have an increased expression of ICAM‐1 on endothelial cells that facilitates immune cell uptake." (PMID 32618430, 2020). "Diabetes mellitus mice showed a significantly reduced expression of Egr-1 endothelial downstream genes Intercellular Adhesion Molecule-1 (ICAM-1) and urokinase Plasminogen Activator (uPA), relevant for extravasation of leukocytes which promote arteriogenesis." (PMID 31284541, 2019). "The results found that capillaries and vascular smooth muscle cell content reduced, and NgBR and ICAM-1 were elevated in rats with diabetic ED." (PMID 31442237, 2019).
diabetes (continued). "A previous study suggests that VEGF injected in naïve eyes triggered many of these vascular changes observed during diabetes, such as ICAM-1 upregulation and vascular permeability." (PMID 29434227, 2018). "Experiments in endothelial cells and STZ-induced diabetes mice by us and others also identified significant attenuation of ICAM-1 and MCP-1 levels, as well as inflammatory responses by metformin." (PMID 29854819, 2018). "Hyperglycemia promotes the accumulation of ECM, such as FN, increases the TGF-β1 expression and promotes the overproduction of inflammation factors, including ICAM-1 in diabetes." (PMID 29621130, 2018). "DR is also known to have an inflammatory component in that leukostasis occurs and increased levels of the adhesion molecule ICAM-1 have been found in the retina of diabetics." (PMID 29046877, 2017). "Intravitreal delivery of miR-146 inhibits the diabetes-induced up-regulation of the NF-κB downstream gene ICAM1, microvascular leakage, and retinal functional defects." (PMID 29074557, 2017). "In the same way, it has been shown that patients with diabetes mellitus type 2 and poor sleep present higher morbidity of cardiovascular diseases than diabetes mellitus patients sleeping normally; those patients also present higher plasma levels of ICAM-1." (PMID 27738642, 2016). "In the large Nurses' Health Study that included 121,700 subjects, s-ICAM-1 level was predictive for the incidence of diabetes." (PMID 26981539, 2016). "Via regulating inflammatory factors, especially for ICAM-1, and lowering uric acid, tubulointerstitial injury is reduced in diabetes." (PMID 27200371, 2016). "Eriodictyol also impeded diabetes-related lipid peroxidation by decreasing the levels of TNFα, intercellular adhesion molecule 1 (ICAM-1), and vascular endothelial growth factor (VEGF)." (PMID 27092490, 2016). "Intervention with daily exposure to the PBM totally inhibited the increase in retinal superoxide, and significantly inhibited diabetes-induced abnormalities in leukostasis, retinal ICAM-1 expression, and spatial frequency threshold (p<0.0001)." (PMID 26426815, 2015). "Although the Icam1 gene is essential for diabetes development in NOD the presence of this deletion shows that the Icam2 gene in the Dvs substrain is dispensable for diabetogenesis." (PMID 25740934, 2015). "PBM intervention improved diabetes-induced changes in superoxide generation, leukostasis, expression of ICAM-1, and visual performance." (PMID 26426815, 2015). "Apart from IL-10, no other changes in cytokine levels in retina or in the expression of ICAM-1 mRNA in retinal vessels were observed in response to diabetes, at least at these early time points and in these mice strains." (PMID 25918731, 2015). "This contrasts with previous findings in C57Bl/6 mice at later time points after 8 weeks of diabetes, in which we were able to detect increased ICAM-1 mRNA in retinal vessels and enhanced levels of TNFα, IL-6, and IL-1β mRNA in whole-retina homogenates." (PMID 25918731, 2015). "Our results demonstrate that ICAM-1 is localized not only in cerebrovascular endothelial cells but also in cortical neurons, implying diabetes leads to enhanced neuro-inflammation in post-ischemic brain tissues." (PMID 25389378, 2014). "Compared to normoglycemic ischemia animals, diabetes aggravated neuronal death, decreased Nissl body staining, and increased ICAM-1 mRNA and protein levels in the frontal cortex." (PMID 25389378, 2014). "Diabetes further increases ischemia-induced ICAM-1 expression at the transcriptional and translational levels." (PMID 25389378, 2014). "The levels of inflammatory mediators (NF-kB, IL-1β, tumor necrosis factor α, and ICAM-1 etc.)are elevated in the retina in diabetes and leukostasis is increased." (PMID 24479616, 2014). "Diabetes induced strong increases in renal ICAM-1 at both the mRNA and protein levels at the 4-week time-point, which were further enhanced at the 8-week time-point." (PMID 24651118, 2014).
diabetes (continued). "With the induction of diabetes, we observed a significant upregulation in ICAM-1 expression in the glomeruli of wildtype Balb/c mice, implicating the contribution of hyperglycemia to the pathogenesis of microvascular inflammation in diabetic nephropathy." (PMID 25303153, 2014). "The results showed that the ICAM-1 mRNA levels were up-regulated after 1, 3, and 6 days of reperfusion in the normoglycemic rats and that diabetes further up-regulated the expression of the post-ischemic ICAM levels." (PMID 25389378, 2014). "Additional anti inflammatory therapies have been reported which decrease diabetes-induced retinal leukostasis and permeability or retinal ICAM1 such as corticosteroids, RAGE inhibitors, and salicylates." (PMID 24205223, 2013). "The expression of ICAM-1 is increased in diabetes, and its specific inhibition prevents diabetic retinal leukocyte adhesion and blood-retinal barrier breakdown." (PMID 23922493, 2013). "Here, we show that diabetes-induced increase in VEGF expression is associated with significant increases in ROS generation, increases in ICAM1 and abnormal accumulation of albumin outside of retinal vessels." (PMID 24358357, 2013). "In the retina, it was shown that diabetes activates induction of proinflammatory mediators such as monocyte chemoattractant protein-1, interleukin-6, intercellular adhesion molecule-1, inducible nitric oxide synthase, matrix metalloproteinase-9, and TNF-alpha." (PMID 24259948, 2013). "The results also indicate that diabetes can elicit the expression of adhesion molecules, including P-selectin, ICAM-1, and VCAM-1, which indirectly or directly promote development of ETD to induce CVD." (PMID 24499567, 2013). "NF-κB has been localized to the inner nuclear layer and ganglion cells of the retina, and NF-κB-regulated inflammatory gene products are reported to be upregulated in the retinas during diabetes such as cyclooxygenase-2, iNOS, ICAM-1, and TNF-α." (PMID 23671886, 2013). "Quantitation of the number of anti-ICAM-1 labeled fluorescent microspheres binding to the luminal surface of the retinal endothelium showed that diabetes significantly increased ICAM-1 expression on retinal vessels in WT animals (WT→WT) two-fold." (PMID 23874797, 2013). "We conclude that ligation of the αmβ2 integrin on leukocytes with a molecule on the surface of endothelial cells (presumably ICAM-1) is critical to the diabetes-induced degeneration of retinal endothelial cells." (PMID 24205223, 2013). "After 12-week administration, we observed that RRP suppressed inflammatory gene expression and NF-κB activation and efficaciously reversed diabetes-induced elevation of ICAM-1 and VCAM-1 levels." (PMID 23662142, 2013). "We also found that deletion of NOX2 or inhibition of NADPH oxidase completely blocked the diabetes-induced increase in ROS production, normalized ICAM-1 and prevented the retinal vascular permeability." (PMID 24358357, 2013). "Many factors contribute to the increase in ICAM-1 production during diabetes including hyperglycemia, shear stress, advanced glycation end products, and oxidative stress." (PMID 22518298, 2012). "Western blotting revealed that both diabetes and Zn deficiency significantly up-regulated the expression of PAI-1, TNF-α, and ICAM-1." (PMID 23251339, 2012). "In this review, we will summarize the genetic and pathophysiological relevance of ICAM1 and discuss about the possible role of ICAM1 in the development of diabetes and DN as well as the perspectives of the ICAM1 research." (PMID 23346076, 2012). "For ICAM-1, those in the top tertile comprised 44% of the individuals with prediabetes or diabetes only and more than 60% of those with MetS plus prediabetes or diabetes but only 29% of those with MetS only have elevated ICAM-1." (PMID 21989115, 2011). "Icam1 and Edn2 are increased with diabetes and show similar magnitude increases in expression with age." (PMID 21633715, 2011).